CLEC12A (C-type lectin domain family 12 member A)
Description:
Myeloid inhibitory C-type lectin receptor that acts as a negative regulator of myeloid cell activation. Myeloid cell inhibition is required to limit proinflammatory pathways and protect against excessive inflammation (By similarity). Specifically recognizes and binds various structures, such as neutrophil extracellular traps (NETs) or monosodium urate crystals. Also acts as a pattern-recognition receptor for pathogen-associated molecules, such as plasmodium hemozoin or mycobacterial micolic acid. Ligand-binding induces phosphorylation of its ITIM motif, followed by recruitment of tyrosine-protein phosphatases PTPN6 and PTPN11, which counteract tyrosine-protein kinase SYK, thereby preventing myeloid cell activation. Acts as a pattern-recognition receptor for NETs in neutrophils: specifically recognizes DNA in NETs, leading to inhibit neutrophil activation and limit further NET formation. This regulation is essential for controlling key neutrophil responses and limit NET-mediated inflammatory conditions (By similarity). Also recognizes dead cells by acting as a receptor for monosodium urate crystals, leading to down-regulate neutrophil activation. Binding to monosodium urate crystals also promotes the type I interferon response (By similarity). Acts as an inhibitor of natural killer (NK) cell cytotoxicity. Also acts as an inhibitor of dendritic cell maturation in an IL10-dependent manner.
Synonyms: CLL-1; DCAL-2; hKLRL1; MICL; CD371; CLL1
Tractability: Antibody: UniProt places it where antibodies can reach, with high confidence; its Gene Ontology location is reachable by antibodies, with high confidence; UniProt predicts a signal peptide or a membrane-spanning region.
Gene: Protein-coding gene on chromosome 12 (9,951,316 to 9,995,694, forward strand). Ensembl gene ENSG00000172322.
Subcellular location: Cell membrane
Pathways (Reactome):
Immune System: Neutrophil degranulation
Gene Ontology:
Molecular function: pattern recognition receptor activity; protein binding; transmembrane signaling receptor activity; signaling receptor regulator activity
Biological process: negative regulation of dendritic cell differentiation; negative regulation of immune response; negative regulation of inflammatory response; negative regulation of natural killer cell activation; negative regulation of neutrophil activation; positive regulation of type I interferon production; signal transduction
Cellular component: plasma membrane; specific granule membrane; tertiary granule membrane
Genetic constraint (gnomAD): Loss-of-function variants: 17 observed, 18.67 expected, observed/expected ratio (o/e) 0.91, 90% interval 0.62 to 1.37. The upper end of that interval is the gene's LOEUF score, 1.37, which puts it in group 5 of 6, group 1 being the genes least tolerant of losing a copy. Missense variants: 243 observed, 230.98 expected, observed/expected ratio (o/e) 1.05, 90% interval 0.95 to 1.17. Synonymous variants: 85 observed, 76.7 expected, observed/expected ratio (o/e) 1.11, 90% interval 0.93 to 1.33.
Homologues: Orthologues: chimpanzee CLEC12A (97% identical), macaque CLEC12A (83% identical), dog CLEC12A (62% identical), guinea pig CLEC12A (57% identical), pig CLEC12A (56% identical), mouse Clec12a (49% identical), rat Clec12a (47% identical), zebrafish si:dkey-26c10.5 (18% identical), Drosophila melanogaster rgn (17% identical), zebrafish si:ch211-170d8.8 (16% identical), zebrafish si:ch211-193e13.5 (14% identical), Caenorhabditis elegans clec-196 (12% identical), and 1 more. Paralogues in human: CLEC1A (29% identical), CLEC12B (28% identical), OLR1 (23% identical), CLEC1B (21% identical), CLEC7A (20% identical), CLEC9A (19% identical), KLRC1 (18% identical), KLRC2 (18% identical), KLRC3 (18% identical), KLRD1 (18% identical), KLRG1 (17% identical), KLRK1 (17% identical), and 11 more.
Diseases named in the same sentence as CLEC12A in open-access papers:
CLEC12A is named in the same sentence as 53 diseases in open-access papers, as found by Europe PMC text mining. Sharing a sentence is not in itself a finding about the gene and the disease. The quoted sentences say what the papers report.
acute myeloid leukemia (29 papers, 2017 to 2025). Acute myeloid leukemia (AML) is a group of neoplasms arising from precursor cells committed to the myeloid cell-line differentiation. "CLEC12A is also a cancer stem cell marker in myelodysplastic syndrome and a therapeutic target in acute myeloid leukemia." (PMID 34830054, 2021). "CLL-1 (also known as CLEC12A) is a transmembrane glycoprotein that is highly expressed in acute myeloid leukemia (AML) blasts, leukemia stem cells (LSCs), and monocytes but has low expression in normal hematopoietic cells." (PMID 37297016, 2023). "MCLA-117, targeting C-type lectin domain family 12 member A (CLEC12A) and CD3, has demonstrated promising effects in the treatment of acute myeloid leukemia in phase I." (PMID 30886871, 2019). "Although the presence of CLEC12A in acute myeloid leukemia is well established, its role in non-hematopoietic tumors is still obscure." (PMID 38144525, 2023). "In acute myeloid leukemia (AML), the expression of the ADGRE2 antigen and CLEC12A antigen is differentially high and low, respectively." (PMID 41348261, 2025).
leukemia (15 papers, 2016 to 2025). A malignant (clonal) hematologic disorder, involving hematopoietic stem cells and characterized by the presence of primitive or atypical myeloid or lymphoid cells in the bone marrow and the blood. "While CLEC12A is primarily associated with leukemia, it has also been shown to sensitize breast cancer cells to artemisinin treatment by suppressing autophagy and inflammation." (PMID 41363115, 2025). "Up to now, numerous leukemia-associated aberrantly expressed markers have been recognized, including CD2, CD7, CD11b, CD22, CD33, CD44, CD45RA, CD56, CD123, CD366 (TIM3) and CD371 (Clec12A)." (PMID 36792658, 2023).
rheumatoid arthritis (10 papers, 2016 to 2025). A chronic, systemic autoimmune disorder characterized by inflammation in the synovial membranes and articular surfaces. "C-Type Lectin Domain Family 12 Member A (CLEC12A) gene (log2FC = 8.16), which encodes a myeloid inhibitory receptor associated with the pathogenesis of rheumatoid arthritis (RA), was the most upregulated in the OA meniscus." (PMID 40724902, 2025). "Studies of rheumatoid arthritis (RA) have also shown that, loss of CLEC12A function or its decreased expression is associated with an increased RA disease activity and inflammation severity." (PMID 37102643, 2023). "We thus postulated that CLEC12A expression on circulating myeloid cells of rheumatoid arthritis patients is associated with disease manifestations." (PMID 34045571, 2021). "Results of the present study are in line with the observed inhibitory effects of CLEC12A signaling on pro-inflammatory signaling and T cell responses in sterile inflammation, immune-mediated colitis, rheumatoid arthritis, and mycobacterial infection models." (PMID 41214106, 2025). "The myeloid C-type lectin-like inhibitory receptor 12A (CLEC12A) regulates immune responses in various pathological contexts, including gout, rheumatoid arthritis, and viral infection." (PMID 34638548, 2021). "In knock-out mouse models of gout and rheumatoid arthritis, a diminution in CLEC12A expression enhances inflammation and disease severity." (PMID 34638548, 2021). "Similarly, low levels of CLEC12A expression by circulating neutrophils and monocytes from early rheumatoid arthritis patients correlate with higher disease activity." (PMID 34638548, 2021). "Moreover, neutrophil and monocyte CLEC12A expression is significantly higher in early rheumatoid arthritis patients at baseline than healthy controls." (PMID 34045571, 2021). "Additionally, CLEC12A is known to contribute to the pathogenesis of rheumatoid arthritis." (PMID 35672358, 2022). "The ability of CLEC12A to regulate signal transduction pathways activated by TNF-α suggests our findings are applicable to other inflammatory diseases, such as rheumatoid arthritis." (PMID 34234773, 2021). "Based on the importance of TNF-α in rheumatoid arthritis and gout, subtraction analysis of phosphoproteins generated by stimulation with TNF-α after cross-linking CLEC12A from those generated by TNF-α alone was performed." (PMID 34234773, 2021).
Arthritis (9 papers, 2016 to 2024). Inflammation of a joint. "The loss of CLEC12A expression in CLEC12A knock-out (KO) mice leads to increased joint inflammation, neutrophil activation, and impaired joint injury resolution caused by collagen-induced arthritis compared to wild-type mice." (PMID 34045571, 2021). "Interestingly, CLEC12A-deficient mice were reported to develop exacerbated arthritis in a collagen antibody-induced model characterized by cell death in the synovium." (PMID 32133013, 2020). "CLEC12A KO mice with collagen antibody-induced arthritis also exhibited increased joint inflammation, neutrophil activation, and impaired resolution of joint injury." (PMID 34234773, 2021). "Reduced CLEC12A expression enhances inflammation in CLEC12A knock-out mice with collagen antibody-induced arthritis." (PMID 34045571, 2021). "Reduced CLEC12A expression enhances myeloid cell activation and inflammation in CLEC12A knock-out mice with collagen antibody-induced or gout-like arthritis." (PMID 34638548, 2021). "Astonishingly, authors proposed that during arthritis development, CLEC12A acts as an autoantigen that modulates threshold of myeloid cell activation." (PMID 32133013, 2020). "Moreover, antibody-induced CLEC12A internalization in wild-type mice enhanced collagen antibody-induced arthritis." (PMID 34234773, 2021). "With regards to CLEC12A, for instance, it may also contribute to the resolution of inflammation in gout since the arthritis phenotype in CLEC12A knock-out mice persists for a significantly longer period of time than in wild-type mice." (PMID 30177932, 2018).
gout (6 papers, 2018 to 2024). A condition characterized by painful swelling of the joints, which is caused by deposition of urate crystals. "Of pertinence to gout, is the production of significantly higher amounts of ROS by CLEC12A deficient, mouse leukocytes partly due to the phosphorylation of the p40phox, a subunit of NADPH oxidase." (PMID 30177932, 2018). "Whether gout flares can be alleviated by activating CLEC12A inhibitory signals or promoting the phagocytosis of MSU crystals by CLEC12A needs to be further investigated." (PMID 38367667, 2024). "A mechanism through which colchicine may dampen a gout attack is by preserving the cell-surface expression of CLEC12A on neutrophils." (PMID 30177932, 2018).
glioblastoma (4 papers, 2013 to 2026). The most malignant astrocytic tumor (WHO grade IV). "ASGR2 and CLEC12A expression was also validated by cytofluorimetric analysis on both tumor and liquid biopsies from 20 glioblastoma patients." (PMID 41898489, 2026). "In primary glioblastoma cases, M1 macrophages were classified by CIBERSORT as monocyte-derived tumor-associated macrophages (Mo-TAMs), based on the expression of genes such as TGFB1, CLEC12A, and FXYD5." (PMID 35203505, 2022). "Since CD81 resides inside the cell membrane of unstimulated microglia, and CLEC12A is expressed at relatively low levels in monocytes, we chose F11R and SELL as representative differentially-expressed flow cytometry markers to study monocyte infiltration in murine glioblastoma." (PMID 24147027, 2013).
viral infection (4 papers, 2020 to 2025). "The cause for different functions of CLEC12A signaling in viral disease models remains speculative but might be attributed to the activation of heterologous signaling pathways by diverse exogenous and endogenous ligands." (PMID 41214106, 2025). "On the other hand, CLEC12A enhances the IFN response following viral infection, thereby enhancing the antiviral immune response, which is diminished and delayed in patients with COVID-19 and is only observed in patients developing critical illness." (PMID 36928077, 2023). "Authors elegantly showed that following viral infection, CLEC12A triggered by MSU released by host dead cells, positively activates a type-I IFN response thereby amplifying anti-viral immune response." (PMID 32133013, 2020). "Moreover, uric acid crystals can be sensed by Clec12A, a regulator of type-I interferon responses, which is a pivotal defensive mechanism against viral infection." (PMID 34025575, 2021). "However, whether this represents a universal effect in viral disorders and whether CLEC12A signaling influences brain pathology in neurotropic virus infections remains undetermined." (PMID 41214106, 2025). "Interestingly, a link between CLEC12A and the type-I IFN response that is important for host immunity against viral infection, was recently demonstrated." (PMID 32133013, 2020). "Authors proposed that as prolonged type-I IFN signaling during chronic virus infection facilitates virus persistence by inducing negative immune regulators, CLEC12A inhibition may be clinically beneficial in cases of persistent infection." (PMID 32133013, 2020).
Autoimmunity (3 papers, 2016 to 2024). The occurrence of an immune reaction against the organism's own cells or tissues. "Not long ago, CLEC12A was shown to sense monosodium urate microcrystals (MSU) from dying cells thereby responding to noninfectious inflammation, giving this receptor importance in autoimmunity and inflammatory disease." (PMID 28578388, 2017).
breast carcinoma (3 papers, 2023 to 2025). "Since till date there is no study elucidating the involvement of CLEC12A in solid tumors, we have attempted to investigate the role of CLEC12A in breast cancer cells, using a mice model." (PMID 38144525, 2023). "In order to further validate our findings, we overexpressed CLEC12A in murine mammary cancer cells (4T1) and human breast cancer cells (MDA-MB-231) and checked the effects in response to ART treatment." (PMID 38144525, 2023). "This further reinstated that CLEC12A downregulation is an absolute necessity for ART-induced apoptosis in mice tumors and breast cancer cells." (PMID 38144525, 2023). "This study thereby established that in non-hematopoietic cells, CLEC12A bypassed the canonical TLR-mediated signaling and adopted an alternative pathway of restraining inflammation and promoting cell death in the presence of ART, in both mice mammary tumors and breast CSCs." (PMID 38144525, 2023).
cerebral malaria (3 papers, 2020 to 2023). A sequestration of Plasmodium falciparum in the brain, which can cause coma and/or seizures. "Mice deficient in CLEC12A were protected from experimental cerebral malaria (ECM)." (PMID 34889727, 2021). "Lately, we identified CLEC12A as a receptor for another crystalline ligand, hemozoin, and showed the crucial role of CLEC12A in the development of cerebral malaria." (PMID 36835297, 2023). "For instance, the myeloid C-type lectin-like receptor (MICL/Clec12a) was shown to cross-prime CD8+ T-cells contributing to the development of experimental cerebral malaria and to promote murine viral lymphocytic choriomeningitis virus (LCMV) infections by hampering pathogen clearance." (PMID 32698416, 2020).
autoimmune disease (2 papers, 2021 to 2024). A disorder resulting from loss of function or tissue destruction of an organ or multiple organs, arising from humoral or cellular immune responses of the individual to their own tissue constituents. "The correlations between CLEC12A expression and cytokine levels strongly suggest that CLEC12A modulates the immune response that drives the early stages of this autoimmune disease." (PMID 34045571, 2021).
Behçet's disease (2 papers, 2017 to 2023). "Patients with severe forms of Behçet's disease underexpress CLEC12A with respect to patients with mild forms of the disease." (PMID 28377641, 2017).
COVID-19 (2 papers, 2023 to 2024). A disease caused by infection with severe acute respiratory syndrome coronavirus 2. "Therefore, analyzing CLEC12A and ACHE gene expression from blood may provide a promising approach for early risk stratification of severely ill COVID-19 patients." (PMID 36928077, 2023). "In addition to CLEC12A, we also identified the time-independent increased expression of ACHE in COVID-19 patients with a worse outcome." (PMID 36928077, 2023). "The identified biomarkers CLEC12A and ACHE might both examine the ability of an individual to inhibit upstream activation of the NF-κB pathway, albeit by different mechanisms, and thus the ability to prevent an overwhelming immune response in COVID-19." (PMID 36928077, 2023). "The significantly lower expression of CLEC12A and ACHE in healthy controls compared to the two COVID-19 patient groups suggests that the expression of these genes might be induced during severe COVID-19 and is probably not a predisposing factor." (PMID 36928077, 2023). "We demonstrated decreased expression of CLEC12A in COVID-19 non-survivors in the ICU." (PMID 36928077, 2023). "In principle, the increased expression of ACHE in COVID-19 non-survivors and the increased expression of CLEC12A in COVID-19 survivors could be due to either COVID-19 itself or might represent an unknown predisposing factor for the development of severe COVID-19." (PMID 36928077, 2023).
influenza (2 papers, 2023 to 2025). An acute viral infection of the respiratory tract, occurring in isolated cases, in epidemics, or in pandemics; it is caused by serologically different strains of viruses (influenzaviruses) designated A, B, and C, has a 3-day incubation period, and usually lasts for 3 to 10 days. "By conjunction with anti-DEC205 or anti-Clec12A antibodies, the OVA protein could provide efficient protection against influenza challenge, especially in the anti-DEC205 antibody fusion construct, indicating that CD103+ DCs could be a more important subtype of lung DCs than CD11b+ DCs." (PMID 38093320, 2023).
lupus (2 papers, 2022 to 2024). "Similar genetic background-dependent association between IFN activity and CLEC12A co-expression patterns is confirmed in systemic lupus erythematosus by in silico analysis, which implies that CLEC12A might be an IFN-regulated gene." (PMID 35672358, 2022).
myeloid neoplasm (2 papers, 2016 to 2018). Proliferation of myeloid cells originating from a primitive stem cell. "Importantly, our findings could add to the deeper understanding of CLEC12A as a blast‐ and cancer stem cell marker in the spectrum of myeloid neoplasms." (PMID 29411522, 2018).
Salmonella Infections (2 papers, 2023 to 2024). Infections with bacteria of the genus SALMONELLA. "In a murine Salmonella infection model, it was shown that CLEC12A contributed to antibacterial autophagy, as CLEC12A was recruited to bacteria–autophagosome complexes and interacted with an E3-ubiquitin ligase complex functionally involved in autophagy." (PMID 36835297, 2023). "Moreover, CLEC12A was found to potentiate the type I IFN responses induced by cytosolic RNA sensors, and to stimulate antibacterial autophagy during Salmonella infection by interacting with the endogenous host proteins." (PMID 36835297, 2023).
brain tumors (1 paper, 2025). "CITE-seq analysis revealed many distinct Mo- vs. Em-Microglia markers, of which some may also help to differentiate Em- from Mo-Microglia during inflammation and disease, such as CLEC12A to distinguish microglia vs. monocyte-derived macrophages infiltrating brain tumors." (PMID 40311613, 2025).
cervical cancer (1 paper, 2025). A primary or metastatic malignant neoplasm involving the cervix. "In addition, CLEC12A is a key marker of tumor-infiltrating immune cells in cervical cancer and reflects the state of the tumor microenvironment." (PMID 41231350, 2025).
Chromoblastomycosis (1 paper, 2025). "The blue cluster is associated with “C-type lectin domain family 12 member A/B (Clec12a/B) and Chromoblastomycosis”." (PMID 41039310, 2025).